IL22 (interleukin 22)
Diseases named in the same sentence as IL22 in open-access papers (continued):
Sharing a sentence is not in itself a finding about the gene and the disease.
infection (continued). "Most studies in skin diseases implicate IL-22 as a pathogenic component in the immune response against infections." (PMID 33003458, 2020). "Recent studies suggest that IL-22 prevents tissue damage caused by inflammation and infection, promotes wound healing, and restores the mucosal barrier integrity of the intestine tissue." (PMID 33381598, 2020). "Gastrointestinal delivery of recombinant REG3G decreased lung inflammatory gene expression and protected Il22−/− mice from weight-loss during infection." (PMID 33488611, 2020). "So far, autoantibodies to interferon (IFN)-γ, GM-CSF, to a group of TH-17 cytokines comprising IL-17A, IL-17F, IL-22, IL-23, and to IL-6 have been found to be causative or closely associated with susceptibility to infection." (PMID 32419033, 2020). "Th17 cells are highly inflammatory cells regulated by Rorγt which produce IL-17, IL-22, and IL-27 and are associated with tissue homeostasis during infection." (PMID 32974217, 2020). "RORγt+ ILCs increased apoptosis in AHR-deficient mice, together with less production of IL-22 and the mice were particularly prone to infection with C. rodentium." (PMID 30804706, 2019). "To explore the novel virulence protein(s) that is critical for CR infection-caused severe mortality and morbidity in Il22-/- mice, we infected Il22-/- mice by oral gavage with each individual mutant strain from the first 5 sub-libraries of CR random mutants." (PMID 31251784, 2019). "In line with the severe mortality, infection with wild-type CR caused more body weight loss and elevated clinical score (referring to both weight loss and diarrhea severity) in Il22-/- mice within 7–14 dpi." (PMID 31251784, 2019). "Patients with autoimmune polyendocrine syndrome type (carrying autoantibodies against IL-22) are more susceptible to various infections including A/E pathogens than healthy controls with normal IL-22 levels." (PMID 31251784, 2019). "IL-22 is a classic Th1-cell-associated pro-inflammatory cytokine that exacerbates ileitis following infection with protozoa, e.g., Toxoplasma gondii." (PMID 31139196, 2019). "In striking contrast, despite similar colonization and proliferation, infections with ΔespG and Δmap strains led to remarkable body weight loss, diarrheal symptoms, and severe mortality with 100% death within 14 dpi in Il22-/- mice, as did wild-type CR." (PMID 31251784, 2019). "In particular, IL-22-mediated epithelial stem cell regeneration is critical to maintain gut homeostasis after genotoxic treatment and pathogenic infection." (PMID 31555282, 2019). "As expected, the mortality rates of Il22-/- mice infected with most randomly mutated strains were comparable to that of animals with wild-type CR infection." (PMID 31251784, 2019). "This approach was validated by our identification of two pathways that were already linked to infection by Mucorales: interleukin-22 (IL-22) and IL-17A." (PMID 30108171, 2018). "Recent studies have shown that IL-22 can be secreted by neutrophils, however infection of IL-22 deficient mice with C. rodentium results in greater CCH." (PMID 30365535, 2018). "Using an antibody-based approach, we demonstrated that IL-22 neutralisation led to increased susceptibility to infection and to lung damage correlated with an increase in neutrophil accumulation in the lungs." (PMID 28887540, 2017). "Mice in which IL-22 had been neutralised displayed aggravated lung damage, increased neutrophilic response and mice susceptibility during infection." (PMID 28887540, 2017). "Neutralising IL22-BP in our model induced a decreased susceptibility of the mice to the infection, decreased lung damage and PMN recruitment as observed with the administration of recombinant IL-22." (PMID 28887540, 2017). "At 1 month post infection, RNA was isolated from the gastric tissue of H. pylori-infected WT and IL-22-deficient mice." (PMID 26867135, 2016).
infection (continued). "Two independent studies demonstrated roles for IL-22 in the intestinal pathophysiology associated with infection with Toxoplasma gondii." (PMID 27055194, 2016). "IL-22-deficient mice and WT mice had similar levels of acute and chronic inflammation as scored from H&E staining of the gastric tissue at 1 month post infection." (PMID 26867135, 2016). "Mice with impaired cells that express IL-22 showed an increase in the susceptibility to infection by C. rodentium, which suggests that commensal bacterial-driven IL-22 produced by ILC3s is important for protection against infectious pathogens." (PMID 28070181, 2016). "Dendritic cells from IL-22-deficient mice express significantly more CD86 compared to dendritic cells from wt mice at this early time point of infection." (PMID 27311945, 2016). "Flow cytometric analysis revealed that the numbers of macrophages (CD90.2−, CD11b+, CD11c+, Gr1−, MHCII+) were unaffected upon IL-22 deficiency (C57BL/6 mice, 0.98 × 106 ± 0.47 × 106; IL-22−/− mice, 1.14 × 106 ± 0.46 × 106 on day 14 post infection)." (PMID 27650379, 2016). "Time points up to 3 months post infection indicate that IL-22-deficient mice are able to control H. pylori colonization just as well as WT mice." (PMID 26867135, 2016). "On day 7-post infection, lung samples were analyzed by qPCR for expression of IL-17 and the Th17-associated cytokines IL-21 and IL-22." (PMID 26942409, 2016). "In this experiment, even with the low dose of infection, the IL-22-deficient mice had lower bacterial burdens in their gastric tissue at 4 weeks post infection compared to WT mice." (PMID 26867135, 2016). "Il22-/- mice developed more severe disease than wild-type mice, with significantly more pathology at the site of infection, and in some cases permanent loss of tissue." (PMID 26285207, 2015). "Infection of lambs was associated with an increase in the expression of the IFNγ and IL22 genes which was evident from as early as 1 dpi with a further increase observed at 3 and 6 dpi." (PMID 25890354, 2015). "We noticed that in addition to greater swelling, the ears of Il22-/- mice often exhibited more severe pathology than wild-type mice, and in some cases led to tissue loss at the site of infection." (PMID 26285207, 2015). "Although IL-17A and IL-22 secretion can be a hallmark of the adaptive phase response to infection, it is becoming increasingly clear that bacterial pathogens trigger rapid IL-17A- and IL-22-dependent innate defense in the gut mucosa." (PMID 25926936, 2015). "Knock-out of IL-22 renders mice more susceptible to infection with S. pneumoniae than wild type animals." (PMID 25119879, 2014). "On the contrary, studies have implicated protective roles for IL-22 in certain intracellular pathogen infections including experimental influenza and dengue infectious models." (PMID 24586147, 2014). "We found elevated levels of IL-22 through the infection in IDO1-deficient mice in which high levels of IL-17F, but not IL-17A, were also higher as compared to wild-type mice." (PMID 23853597, 2013). "In mouse models of infection, IL-22 was implicated in development of Rhizomucor spp.-induced skin lesions." (PMID 23798999, 2013). "The course of the infection was different in IL-22- vs. IDO1-deficient mice and in those mice vs. their respective wild-type counterparts." (PMID 23853597, 2013). "After infection with Nippostrongylus brasiliensis, a rodent hookworm, IL-22-deficient mice showed impaired worm expulsion despite normal levels of type 2 cytokine production." (PMID 24130494, 2013). "It has previously been shown that the induction of IL-22 expression upon pathogen colonization is important, as IL-22 -/- mice are more susceptible to infection." (PMID 22046427, 2011). "Enhanced IL-22 levels have been linked to various states of immunoactivation as seen in the context of infection, autoimmunity, and allergic disorders." (PMID 20976193, 2010).
infection (continued). "Moreover, CR elicits lethal infection in GF Rag1-/- mice that harbor distinct host deficiencies from GF Il22-/- animals, further strengthening the notion that CR harbors gut microbiota-independent virulence." (PMID 39630719, 2024). "However, C57BL/6 Il22−/− mice succumb to the infection, similar to C. rodentium-susceptible mouse lines such as C3H/HeJ mice." (PMID 38557196, 2024). "T cell–associated cytokines IL-17 and IL-22 were significantly increased in mice immunized with vaccine + anti–IL-10 when compared with control groups, and production was also sustained up to day 10 after infection." (PMID 38973612, 2024). "Therefore, despite the reduction in conventional T lymphocytes over the course of the infection, in non-IL-22-deficient animals, the production of this cytokine can be sustained by these populations throughout the infection." (PMID 39635124, 2024). "We find that both resident and recruited γδ T cells are part of this induced wound healing response via production of IL-17A and IL-22, as well as the induction of IL-10 in other cells, and that a deficit in γδ T cells causes a profound increase in tissue pathology following infection." (PMID 38543790, 2024). "In addition, indole derivatives can protect intestine against pathogenic infection and limit mucosal inflammation by stimulating IL-22 expression via activating AhR." (PMID 37362931, 2023). "Here, we analyzed bulk bladder transcriptomic data in an unbiased way and asked which pathways were most up-regulated in the context of infection, identifying type 17-associated transcripts (including Il22, Il17, Rorc) as the major axis induced post UPEC challenge." (PMID 35845169, 2022). "Th17 cell and γδ T cells have previously been described in the bladder, but given the increase in Il17 and Il22 transcripts at early time points post infection, even in T cell-deficient mice, we sought to characterize bladder ILC3s, as previous reports had described only CD4+ ILC3." (PMID 35845169, 2022). "Herein, the relative expression fold change values of IL-4 and IL-13 were next to those of IL-23, IL-1β, and IL-22, suggesting that a higher expression of Th2-associated cytokine genes coincided with the increased percentage of Th2 cells after infection with intravenous injection." (PMID 33441700, 2021). "The cytokine IL-22 is induced in immune cells upon infection with pathogenic bacteria." (PMID 34074061, 2021). "Therefore, loss of IL-22 production gives rise to dissemination of intestinal bacteria, producing chronic body inflammation and resulting in susceptibility to infections, such as Citrobacter rodentium." (PMID 34659248, 2021). "This study suggests that variants in the IL-22 gene may produce different roles in the vulnerability to infection in populations with diverse ethnic backgrounds." (PMID 32148440, 2020). "IL22 can mediate heme-associated iron scavenging away from pathogens during systematic infection." (PMID 32851030, 2020). "Indeed, studies have shown that the induction of antimicrobial peptides, which act as an interface between epithelial cells and microbiota, are a critical aspect of IL-22 action against pathogenic infections." (PMID 33003458, 2020). "In addition, IL-22 deficient mice (Il22−/−) succumbed to infection, which correlated with reductions in the numbers of CD4+ IFN-γ+ T cells, reduced IFN-γ levels, and diminished nitric oxide synthase type 2 (NOS2) expression in the lungs." (PMID 32517114, 2020). "Furthermore, we observed that IL-22 deficiency promoted increased accumulation of neutrophils and macrophages 14 days after infection." (PMID 32517114, 2020). "Up to now autoantibodies to four major groups of cytokines—IFN-γ, GM-CSF, to a group of TH-17 cytokines comprising IL-17A, IL-17F, IL-22, IL-23, and to IL-6—have been found to be causative or closely associated with increased susceptibility to selective infection." (PMID 32419033, 2020).
infection (continued). "However, deletion of espF completely abolishes the CR infection-dependent TJ disruption, epithelial barrier loss, and severe lethality in Il22-/- animals." (PMID 31251784, 2019). "Moreover, histological analyses revealed that wild-type CR infection caused severe damage to colon epithelial tissue in Il22-/- mice, characterized by intestinal crypt elongation, goblet cell depletion, and immune cell infiltration." (PMID 31251784, 2019). "Moreover, EspF deletion markedly attenuated CR infection-caused TJ disruption in the colon and systemic dissemination of CR in infected Il22-/- animals." (PMID 31251784, 2019). "To examine whether the known TJ-disrupting effectors EspF, EspG, Map, and NleA execute redundant functions at colonic epithelia during CR infection in vivo, we assessed their relevance in CR infection-caused mortality in Il22-/- mice." (PMID 31251784, 2019). "The low circulating IL-22 levels in human neonates was speculated to be a significant risk factor for serious infections in the neonatal period." (PMID 31251784, 2019). "The finding of PIV cleavage of IL-22 in sputum from Pseudomonas pneumonia patients suggested that PIV could render the lung susceptible to severe infection by not only P. aeruginosa but also other pathogens." (PMID 31443433, 2019). "Treatment of Hic1Rorc mice with recombinant IL-22 on days -2, -1, 0, 1, 3, 5 and 7 during C. rodentium infection resulted in significant protection from infection, as measured by reduced weight loss, less intestinal pathology and a lack of bacterial dissemination to the liver." (PMID 29470558, 2018). "Our model also revealed a robust inflammatory response at the infection site characterized by the upregulation of genes encoding major pro-inflammatory cytokines, such as Il1b, Tnfa, Il22, several chemokines and chemokine receptors, complement factors, and pattern recognition receptors (PRR)." (PMID 30143654, 2018). "It is now becoming increasingly clear that reduced IL-17 and IL-22 production during infection cannot be attributed solely to the loss of TH17/TH22 cells and that early depletion of ILC may also contribute to this process." (PMID 29326704, 2017). "Hence, large intestinal IL-6 secretion as well as TNF and IL-18 mRNA levels were higher in NOD2−/− as compared to WT mice upon pathogenic infection, whereas C. jejuni induced colonic IL-22 down-regulation occurred in WT mice only." (PMID 28127403, 2017). "This is in line with data showing that mice with a CD11c-specific deletion of MyD88 display enhanced susceptibility towards infection with C. rodentium, which could be rescued by hydrodynamic injection of a plasmid expressing IL-22." (PMID 28520792, 2017). "IL-22−/− mice showed a significantly increased body weight loss during early infection, which could be a sign for pathology." (PMID 27650379, 2016). "The most striking effect of IL-22 was in relation to infection-associated weight loss." (PMID 27375092, 2016). "Indeed, IL-17 and/or IL-22 associated protection has been described for numerous infections, including Citrobacter rodentium, Klebsiella pneumonia, Toxoplasma gondii, Candida albicans, Bordetella pertussis, Pneumocystis carinii, among others." (PMID 26829644, 2016). "Two months after infection the CD11b+Ly6G+ cell response was lower in the lung of IL-17RA- and IL-17RA-IL-22-deficient mice, compared to wild type mice and IL-22-deficient mice, whereas monocytic CD11b+Ly6C+ cells were decreased in IL-22-deficient mice." (PMID 27853279, 2016). "Alternatively, other Th17-associated cytokines, such as IL-22, may be important or may synergize with IL-17 to control this infection." (PMID 19759900, 2009). "However, IL-22 has a protective role during CR infection and Il22-/- mice are susceptible to CR." (PMID 40591723, 2025).
infection (continued). "We observed that CR-caused mortality in SPF Il22-/- mice occurred noticeably slower compared with that in GF Il22-/- animals, indicating that gut microbiota could protect the host against CR infection." (PMID 39630719, 2024). "However, when GPR43 is missing, as shown in knock-out mice, ILC3 proliferation is dampened and ILC3-derived IL-22 levels are reduced, consequently rendering mice more susceptible to gut injury and infection, indicating a microbiota-dependent regulation of ILC3 function." (PMID 36430676, 2022). "Next, at the steady state or during AIEC infection, loss of Il-22 in mice caused a significant decrease in Ki67+ proliferating TA cells, which is consistent to previous studies where injection of IL-22 into mice increases epithelial proliferation and expands TA compartments." (PMID 35169117, 2022). "The early infection (3 dpc) triggered a strong transcriptional up-regulation of many immune genes in different organs including those encoding pro-inflammatory cytokines IL-1β, IL-6 and TNFα and other cytokines involved in the development of adaptive immunity (IL-8, IL-10, IL-22, IL-17C2, INFγ)." (PMID 34497310, 2021). "However, recent research also points to a protective role for the microbiota during murine RV (strain EDIM) infection, by demonstrating high susceptibility to RV infection in Ab-treated and germ-free animals and highlighting a role of microbiota-induced IL22 expression as an anti-viral mediator." (PMID 34356911, 2021). "Similarly, to our observations, IL-22 was crucial for animal resistance and the control of yeast replication, while its deficiency promoted increased neutrophil infiltration into sites of infection." (PMID 32517114, 2020). "Importantly antibody blockade of IL-17 and IL-22 reduced the pathology associated with infection." (PMID 30873151, 2019). "However, IL-17 (including increased expressions of Il17a, Il1a and Il22) and granulocyte-associated (L10 and L11) responses were most pronounced during B. pseudomallei infection, with this infection also exhibiting increased IFN gene signatures (L5 and L7) in contrast to the C. albicans infection." (PMID 31253760, 2019). "Mice deficient in IL-17 had reduced B cell follicle formations during early stages of Mtb challenge, while IL-22-deficient mice had impaired follicle formation at an intermediate stage, although neither of these deficiencies impacted the mouse's ability to control the infection." (PMID 30761149, 2019). "We hypothesized that the reduced levels of IL-22 were responsible for susceptibility to infection." (PMID 29470558, 2018). "Since anti-microbial peptides are well-known as targets of IL-2225, the failed induction of anti-microbial peptides in response to higher IL-22 in PFOS treated mice at late phase of infection may due to a damage of epithelial cells caused by overt inflammation." (PMID 28701769, 2017). "There may yet be a pathological effect of IL-22 in promoting systemic and airways inflammation, perhaps regulated by IL-17, which was undetected in the present study but which exacerbates the weight loss associated with infection." (PMID 27375092, 2016). "Consistently, Trmt61aΔRorc mice displayed markedly reduced percentages and numbers of total ILC3s and IL-22-producing ILC3s in the colon five days post-infection, compared to controls, along with a decreasing trend in the numbers of IL-17A-producing ILC3s." (PMID 41484094, 2026). "As protective factors against K. pneumoniae, IFN-γ and IL-22 levels increased in WT mice during infection." (PMID 41532069, 2026). "In vitro studies showed that nicotine affects the IL-22 axis, inhibiting the production of IL-22 by T cells, thereby weakening the immune barrier of lung epithelial cells against infection." (PMID 40650213, 2025). "Among them, IL-22 functions as an important mediator of the crosstalk between ILC3s and IECs under steady-state and infection conditions." (PMID 41467015, 2025).